C1orf52 (chromosome 1 open reading frame 52)
Synonyms: GM117; FLJ44982
Tractability: PROTAC: ubiquitination databases record sites on it; its protein half-life has been measured.
Gene: Protein-coding gene on chromosome 1 (85,249,953 to 85,259,672, reverse strand). Ensembl gene ENSG00000162642.
Subcellular location (Human Protein Atlas): Nucleoplasm
Gene Ontology:
Molecular function: RNA binding
Cellular component: nucleoplasm
Genetic constraint (gnomAD): Loss-of-function variants: 4 observed, 14.89 expected, observed/expected ratio (o/e) 0.27, 90% interval 0.13 to 0.62. The upper end of that interval is the gene's LOEUF score, 0.62, which puts it in group 2 of 6, group 1 being the genes least tolerant of losing a copy. Missense variants: 216 observed, 216.12 expected, observed/expected ratio (o/e) 1, 90% interval 0.89 to 1.12. Synonymous variants: 101 observed, 86.29 expected, observed/expected ratio (o/e) 1.17, 90% interval 1 to 1.38.
Homologues: Orthologues: chimpanzee C1H1orf52 (100% identical), macaque C1H1orf52 (99% identical), rabbit C1orf52 (95% identical), dog C1orf52 (94% identical), guinea pig C1orf52 (92% identical), mouse 2410004B18Rik (85% identical), rat C2h1orf52 (85% identical), pig C1orf52 (80% identical), zebrafish C23H1orf52 (54% identical).